INS (insulin)
Diseases named in the same sentence as INS in open-access papers (continued):
Sharing a sentence is not in itself a finding about the gene and the disease.
type 2 diabetes (continued). "Here we have shown that this treatment, which led to a 10% sustained weight loss, was also successful in modifying risk markers associated with cardiovascular disease and type 2 diabetes by reducing waist-circumference and fasting insulin as well as increasing HDL-cholesterol concentrations." (PMID 24516621, 2014). "In conclusion, loss of function of EXT proteins may affect beta-cell mass and insulin secretion capacity in humans, and render subjects at a higher risk of developing type 2 diabetes when exposed to environmental risk factors." (PMID 25541963, 2014). "Insulin has been hypothesized to be a cancer growth promoter which could explain an increased cancer risk in adults with type 2 diabetes." (PMID 23437204, 2013). "An important relationship between depressive symptoms and a heightened metabolic risk for type 2 diabetes, including prediabetes and impairment of β-cell function relative to insulin sensitivity, was observed in obese adolescents by a recent study conducted in the USA." (PMID 24282635, 2013). "Notably, -43 (G) is considered the type 2 diabetes risk allele in some studies, while it confers improved insulin secretion in others." (PMID 24059590, 2013). "Obesity is known to be an important risk factor for type 2 diabetes, and the serum level of insulin could be responsible, in part, for mediating the putative positive association between type 2 diabetes and higher BMD." (PMID 24358252, 2013). "Indeed, recent studies increasingly suggest that impaired insulin trafficking is one of the events underlying the pathogenesis of type 2 diabetes." (PMID 23630453, 2013). "This variant could regulate insulin secretion and blood TG levels through regulating the activity of glucokinase in the liver, while it was also correlated with type 2 diabetes." (PMID 23990951, 2013). "Knowing that depression is also more common in people with type 2 diabetes who have co-morbid chronic conditions, studies examining the association between depression and insulin initiation should take the potential confounding role of these co-morbid conditions into account." (PMID 24223860, 2013). "Like obesity has become a global epidemic and a risk factor for diabetes type 2, also the vitamin D endocrine system could be involved in glucose homeostasis and in insulin release mechanisms." (PMID 23924693, 2013). "These GLP-1 RA/basal insulin combinations may be particularly advantageous for obese patients with long-standing type 2 diabetes for mitigating the weight gain associated with insulin therapy, improving glycaemic control, and/or reducing insulin requirements." (PMID 23061470, 2013). "Association of rs9939609 variant with higher FBG, plasma insulin, and leptin levels indicates that this polymorphism may disturb the metabolism in adult females and predispose them to obesity and type 2 diabetes." (PMID 24102053, 2013). "In addition, changes in treatment requirement with time in Type 2 diabetes also primarily relate to progressive loss of insulin secretion capacity." (PMID 23413806, 2013). "Type II diabetes is associated with insulin resistance and reduced insulin secretion." (PMID 23805182, 2013). "Impaired insulin action is a major risk factor for type 2 diabetes development." (PMID 23463496, 2013). "Therefore, only a relative insulin deficiency exists with type 2 diabetes as the day-long circulating insulin concentrations in patients are almost comparable or slightly elevated in absolute terms to the values in normal individuals." (PMID 24151620, 2013). "Some studies have shown that insulin sensitivity is significantly lower in hyperuricemic subjects, suggesting that hyperuricemia causes type 2 diabetes maybe through impaired insulin sensitivity." (PMID 24205181, 2013). "Furthermore, physical activity is linked with lowered blood pressure, improved glucose intolerance, insulin sensitivity and lowered risk of type 2 diabetes." (PMID 24206898, 2013).
type 2 diabetes (continued). "Additionally, abnormal lipid accumulation impairs insulin sensitivity in the liver, contributing to increased hepatic glucose production, hyperglycemia, and glucose intolerance in obesity-associated type 2 diabetes." (PMID 24358267, 2013). "Reduced insulin secretion and beta cell loss, are the major hallmarks of type 2 diabetes." (PMID 24069189, 2013). "The present study found that insulin therapy was associated with a higher relative risk of liver cancer, but not related with other site-specific cancer and overall cancer risks in patients with type 2 diabetes." (PMID 23308218, 2013). "There is also growing evidence that CSII decreases cardiovascular risk factors in poorly controlled type 2 diabetes, suggesting that synchronization of sufficient insulin peaks with meal ingestion and continuous pulsatile infusion of basal insulin corrects metabolic derangements." (PMID 24347835, 2013). "Thus, unraveling the molecular mechanisms underlying insulin resistance would improve setting up preventive and treatment strategies of type 2 diabetes." (PMID 23894607, 2013). "Our results suggested that the presence of the Ala allele may contribute to improved insulin secretory capacity and may confer protection from type 2 diabetes and obesity in the Chinese population." (PMID 23991018, 2013). "With an estimated 870 000 people with insulin‐treated Type 2 diabetes in the UK, the development of absolute insulin deficiency in even a small proportion could have significant impact on both individuals and society." (PMID 23659458, 2013). "The further elucidation of interactions of inflammatory processes with insulin resistance/beta cells failure, as well as with additional factors of the metabolic syndrome, should advance our understanding of the causes of current epidemic of type 2 diabetes." (PMID 23806173, 2013). "In addition, high iron stores have been proposed to contribute to the development of type 2 diabetes by causing pancreatic beta cells damage and insulin resistance through heightening the level of oxidative stress." (PMID 24098686, 2013). "Furthermore, reduced islet GLP1R levels associate with lower insulin secretion, which is seen in patients with type 2 diabetes." (PMID 23879380, 2013). "Therefore, the exact mechanisms underlying the association between a high risk of liver cancer and insulin use in type 2 diabetes are still unclear and further clinical and laboratory studies are required to clarify these mechanisms." (PMID 23308218, 2013). "Likewise, using a network approach a set of genes associated with insulin signaling and nuclear receptors were identified in type 2 diabetes models." (PMID 24376773, 2013). "There is evidence stating that in order to maintain normal levels of blood glucose, African Americans have a compensatory increase in beta cell function; however, progressive loss of the ability to compensate for a decreased in insulin sensitivity increases the risk of type 2 diabetes." (PMID 31667005, 2013). "Therefore, the primary objective of the present study was to survey the overall and site-specific cancer risk in Chinese patients with type 2 diabetes who were treated with human insulin." (PMID 23308218, 2013). "On the other hand, there remains a significant challenge to document whether childhood obesity is or is not an independent risk factor for adult metabolic syndrome, type II diabetes, or biomarkers of the same (blood lipid status, insulin levels, etc.)." (PMID 24079609, 2013). "Another possible mechanism, involving insulin resistance which is diminished when the stomach and upper intestine are bypassed, could be effective if this were indeed the main cause of type 2 diabetes in the present context." (PMID 23849268, 2013). "In summary, accumulating cardiovascular risk factors with insulin-treated type 2 diabetes, increased low-grade inflammation together with altered clot structure and platelet aggregation, may partly explain ATF in these patients." (PMID 23976993, 2013).
type 2 diabetes (continued). "Subjects with type 2 diabetes are at significantly higher risk for many forms of cancer and it has been hypothesized that chronic insulin treatment might facilitate neoplastic growth 72,73." (PMID 23061470, 2013). "SNPs were selected from association results of type 2 diabetes (11 SNPs), obesity (nine SNPs), BMI (three SNPs), waist circumference (one SNP), fasting glucose (seven SNPs), fasting insulin (eight SNPs), fasting HDL-cholesterol (two SNPs) and fasting triacylglycerol (one SNP)." (PMID 23160641, 2013). "Several studies found that insulin use was associated with risk for mortality in type 2 diabetes." (PMID 23308218, 2013). "The number of individuals diagnosed with type II diabetes, which is caused by the ‘metabolic syndrome’ – obesity, insulin resistance and/or abnormal insulin secretion, is increasing worldwide, and creating a strong demand for the development of more effective anti-diabetic drugs." (PMID 23977329, 2013). "Type 2 diabetes (T2D) is caused by a problem in the way body makes or uses insulin." (PMID 23566173, 2013). "In conclusion, we have shown that absolute insulin deficiency is present in 3% of insulin‐treated subjects with Type 2 diabetes and may be detected using UCPCR." (PMID 23659458, 2013). "The VNTR upstream of the INS gene has also attracted a considerable interest in medical genetics, as its length has been associated with type 1 and type 2 diabetes, latent autoimmune diabetes in adults (LADA), polycystic ovary syndrome as well as with size at birth." (PMID 24023707, 2013). "A functional polymorphism of the DDAH2 gene may confer increased risk for type 2 diabetes by affecting insulin sensitivity throughout increased ADMA levels." (PMID 22558392, 2012). "In addition to the clinical features of hyperandrogenism and chronic anovulation, many PCOS women are insulin resistant and are at high risk to develop type-2 diabetes." (PMID 22384174, 2012). "The first observations date back to the famous Rotterdam study, revealing that type 2 diabetes doubled the risk of patients to develop Alzheimer-type dementia, while individuals suffering from type 1 diabetes and receiving insulin therapy had four times the risk." (PMID 22369239, 2012). "Magnesium as a cofactor for several enzymes for glucose metabolism and the inverse association reported between magnesium intake and risk of type 2 diabetes in a meta-analysis of seven cohort studies supports a potential role of magnesium in glucose homeostasis and insulin action." (PMID 22415230, 2012). "Hence, chronically impaired insulin signaling and associated downstream alterations in skeletal muscle tissues make adult Goto-Kakizaki rats a suitable animal model of type 2 diabetes." (PMID 22523676, 2012). "Whereas adequate insulin dosage and adherence to diabetic diet are required to reverse hepatopathy in type 1 diabetes, weight loss helps improvement of insulin insensitivity in type 2 diabetes and ultimately inhibits lipolysis." (PMID 23039762, 2012). "Type 2 diabetes is associated with impaired glucose metabolism and insulin insensitivity." (PMID 23213294, 2012). "It is possible, although unlikely, that the high glucose levels and metabolic disturbance before the start of insulin therapy might trigger leukemia, in an analogous fashion to the increased risk of cancer associated with type 2 diabetes." (PMID 22745776, 2012). "Insulin sensitivity, insulin secretion, and their interaction are underlying mechanisms in type 2 diabetes and its development, with a particularly high type 2 diabetes risk for the combination of the lowest tertiles of insulin sensitivity and insulin secretion." (PMID 22066936, 2012). "Although the association of rs5945326 with HOMA-IR was still not statistically significant after correction for multiple testing errors, the rs5945326-A allele may confer susceptibility to type 2 diabetes by reducing insulin sensitivity." (PMID 23029454, 2012).
type 2 diabetes (continued). "FoxO1 regulation of VEGF-A/islet vascular formation may contribute to compensatory β cell hyperplasia against peripheral insulin resistance, a hallmark of type 2 diabetes." (PMID 22384192, 2012). "In addition, the “inverse” correlation between disease risk and lower BMI was replicated for 6 other type 2 diabetes risk loci, which had been all suggested to affect insulin secretion." (PMID 23173044, 2012). "Several experimental and epidemiological studies have suggested that insulin therapy could produce a substantial increase in the risk of cancer in patients with type 2 diabetes, partly explaining differences in incidence with respect to nondiabetic subjects." (PMID 23209929, 2012). "However, some of these variably erased CGIs (VECs) remained methylated at all stages, including in mature oocytes and sperm, for example a CGI in the Exoc4 gene which is associated with type 2 diabetes and involved in insulin-stimulated glucose transport." (PMID 23219530, 2012). "Moreover, the increase in the basal insulin secretion in type 2 diabetes with obesity is associated with a decrease in the β-cell's intracellular stores that cannot be offset by commensurate free fatty acid induction of proinsulin biosynthesis." (PMID 22470529, 2012). "Additionally, it is now recognized that IL-1β, for which levels were significantly higher in our First Nations sample, is implicated in the disruption of insulin signaling and the severity of type 2 diabetes." (PMID 22768323, 2012). "The importance of certain micronutrients as cofactors in glucose metabolic pathways, pancreatic β-cell function and in the insulin signaling cascade suggests that deficiency in these micronutrients may play a role in the development of type 2 diabetes." (PMID 22462011, 2012). "Accumulating evidence suggests that deleterious ER stress and excessive intracellular lipids in nonadipose tissues, such as myocyte, cardiomyocyte, and hepatocyte, cause pancreatic β-cell dysfunction and peripheral insulin resistance, leading to type II diabetes." (PMID 22506114, 2012). "Furthermore, in a prospective observation, ALT levels were associated with a decline in hepatic insulin sensitivity and the development of type 2 diabetes." (PMID 22947097, 2012). "Moreover, what is the proper basal insulin to total daily insulin dose ratio and the associated factors in Chinese type 2 diabetic patients are yet to be determined." (PMID 22720003, 2012). "From a pathophysiological point of view, insulin-induced up-regulation of myocardial SERCA2a may be seen as a feedback mechanism in handling the volume overload caused by high glucose levels in the early phase of type 2 diabetes, when insulin levels are high." (PMID 22621761, 2012). "In conclusion, our data indicate that a functional polymorphism in the DDAH2 gene may confer increased risk of type 2 diabetes by affecting insulin sensitivity due to an increase in circulating ADMA levels." (PMID 22558392, 2012). "In addition, magnesium intake has been shown to decrease insulin levels and is associated with a lower risk of type 2 diabetes, a potential risk factor for colorectal cancer." (PMID 22415230, 2012). "Thus, the present results indicate that BPA disrupts insulin signaling in peripheral tissues and is likely a risk factor for the development of type 2 diabetes." (PMID 22470480, 2012). "It will be interesting to explore whether the loci associated to type 2 diabetes in African Americans are also associated with impaired insulin secretion, once genome-wide association studies of sufficient power are carried out." (PMID 22438884, 2012). "Consequently, an elevated demand of insulin is controlled by increased proliferation of pancreatic endocrine cells while insufficient insulin secretion and the development of type-2 diabetes have been associated with β-cell death." (PMID 22216119, 2011).
type 2 diabetes (continued). "It has been reported that the formation of pancreatic islet amyloid deposits correlates with loss of β cell mass and progressive decline of insulin secretion, suggesting a close relationship between islet amyloid deposition and the development of type 2 diabetes." (PMID 21589925, 2011). "In type-2 diabetes, inflammation and activation of mono-cytes are postulated to be important for enhancing insulin resistant and may contribute to the loss of insulin secretory function of islet cells." (PMID 27672250, 2011). "However, the ‘birth-weight-lowering’ variant of ADCY5 was associated with elevated glucose and decreased insulin response in early adulthood which argues for a common genetic cause of low birth weight and risk of type 2 diabetes." (PMID 21712988, 2011). "It has been suggested that FFAR1 may play a role in insulin sensitivity, lipotoxicity and is associated with type 2 diabetes." (PMID 21552566, 2011). "Since FFAR1 has been linked to beta-cell function and type 2 diabetes, it is possible that changes in insulin metabolism could impact on energy homeostasis and consequently BMI and body composition." (PMID 21552566, 2011). "Hence, our patients represent a high-risk group for CVD, despite suboptimum insulin treatment of type 2 diabetes and medical therapy of associated comorbidities." (PMID 21756323, 2011). "We also examined abdominal adipose cell size in relation to insulin sensitivity measured with a euglycemic clamp in the Gothenburg group of 166 non-obese individuals (BMI<28 kg/m2) with a known genetic predisposition for Type 2 diabetes." (PMID 21532749, 2011). "Whether minute increases in mean blood glucose may have long-term clinical importance remains unknown; however, it is well known that long-term β-cell stress with elevated insulin production is associated with development of type II diabetes." (PMID 23724225, 2011). "In the liver, there is a balance between insulin and cAMP signaling pathways and dysregulation of this equilibrium has been suggested to be one of the underlying mechanisms involved in the development of type 2 diabetes." (PMID 21533282, 2011). "Moreover, insulin sensitivity was improved in the CD-1 mice that have genetic susceptibility to obesity and type 2 diabetes by feeding a diet containing soy." (PMID 20480025, 2010). "Elevating insulin levels that are not accompanied by elevations in glucose levels indicate a reduced sensitivity to insulin, which may ultimately increase the risk of developing noninsulin-dependent diabetes (i.e., type 2 diabetes)." (PMID 20414467, 2010). "Collectively, these data suggest that air pollutants may increase the risk of type 2 diabetes by impairing insulin sensitivity and point toward inflammatory processes as a mechanistic link." (PMID 20504758, 2010). "Consequently, we measured circulating levels of insulin and leptin by ELISA, and found them to be elevated in MyD88-deficient mice, suggesting type 2 diabetes." (PMID 20824098, 2010). "This relationship which is apparently disconnected from insulin sensitivity may be part of some pathogenetic mechanisms underlying obesity and type 2 diabetes." (PMID 20830305, 2010). "Taken together, the U-shaped relationship between the levels of alcohol intake and the risk of type 2 diabetes might be explained by altered insulin sensitivity and impaired beta-cell function." (PMID 21092093, 2010). "Atherogenic dyslipidaemia (characterized by elevated triglycerides and low HDL-C) is strongly associated with insulin-resistant states, such as type 2 diabetes and the metabolic syndrome, and is also a common finding among patients receiving treatment for dyslipidaemia." (PMID 21532777, 2010). "A variant of the CDKAL1 gene was reported to be associated with type 2 diabetes and reduced insulin release in humans; however, the role of CDKAL1 in β cells is largely unknown." (PMID 21151568, 2010).